DNMT3A (DNA methyltransferase 3 alpha)
Diseases named in the same sentence as DNMT3A in open-access papers (continued):
Sharing a sentence is not in itself a finding about the gene and the disease.
melanoma (continued). "Therefore, we functionally validated METTL4 and DNMT3A using shRNA-mediated knockdown and found that their knockdown in melanoma cells led to melanoma cells growth inhibition." (PMID 31217906, 2019). "However, when examined in Oncomine dataset we found only two genes (METTL4 and DNMT3A) were significantly overexpressed in melanoma samples versus normal skin samples and matched with the results of The Human Protein Atlas data." (PMID 31217906, 2019). "Our comprehensive analysis on the RNA modification regulatory proteins led us to conclude that METTL4 and DNMT3A are the candidates that showed consistent increase in the RNA as well as protein expression of melanoma samples using TCGA, Oncomine and The Human Protein Atlas data." (PMID 31217906, 2019). "Silencing DNMT3A results in dramatic inhibition of melanoma growth and metastasis." (PMID 29717263, 2018). "Indeed, it was showed that knockdown of DNMT3A would upregulate the expression of some immune response genes in melanoma." (PMID 28423585, 2017). "Taken together, these results suggest that BRAFV600E might initiate genome-wide epigenetic modifications through the regulation of DNMT3A, facilitating the initiation of melanoma tumorigenesis." (PMID 25890285, 2015). "UHRF2 protein expression levels in our western blots were not correlated with changes in global methylation or PD-L1 expression, although additional investigations of the relationship between UHRF2, DNMT3A, PD-L1, and global hypomethylation in melanoma may still be warranted." (PMID 30240750, 2018). "To further interrogate the role of DNMTs in melanoma-STING silencing, we transfected B16-F10 cells with small interfering RNA (siRNA) targeting DNMT1, DNMT3A, and DNMT3B." (PMID 36949064, 2023). "SUV39H1/DNMT3A-dependent methylation of the RB1 promoter stimulates PIN1 expression and melanoma development." (PMID 33234142, 2020). "We also performed functional validation studies for DNMT3A and METTL4 and found that they are potentially important for melanoma growth." (PMID 31217906, 2019). "Collectively, in this study, we investigated the epitranscriptomic landscape of melanoma using various publicly available database and identified DNMT3A and METTL4 as the most relevant potential regulators of melanoma growth." (PMID 31217906, 2019). "As an effector, DNMT3A senses the TGF-β signal and modifies TET2 and TET3 promoters to induce the EMT-like process and metastasis in melanoma." (PMID 27852070, 2017). "As an effector, DNMT3A senses the TGF-β signal and silences TET2 and TET3 promoters to induce the EMT-like process and metastasis in melanoma." (PMID 27852070, 2017). "Cell survival was significantly inhibited by T-dCyd in breast BT549, lung NCI-H23, melanoma SKMEL5 and renal ACHN cancer lines harboring deleterious TET2 and nonsynonymous DNMT3A mutations compared to 13 lines without such mutation pattern (P = 0.007)." (PMID 34039392, 2021). "miR-29 may elicit its tumor suppressive potential by repressing targets such as AKT3, DNMT3A/B, or MCL1; however, miR-29 hairpin inhibitors failed to increase the expression of these validated targets in A375 melanoma cells." (PMID 33808771, 2021). "The results obtained in both Riker and UALCAN datasets show that both DNMT3A and METTL4 expression in upregulated in metastatic melanoma samples and hence these genes may play an important role in melanoma growth and progression." (PMID 31217906, 2019). "However, we also observed that both DNMT3A and METTL4 are significantly overexpressed in skin squamous cell carcinoma, skin basal cell carcinoma as well as in melanoma metastatic samples in Riker melanoma dataset set." (PMID 31217906, 2019).
melanoma (continued). "TET2 and TET3 are silenced in melanoma cells by epigenetic mechanisms triggered by TGF-β and mediated by DNA methyltransferase 3A (DNMT3A); these events play a functional role in the epithelial-to-mesenchymal transition (EMT) and in metastatic processes of melanomas." (PMID 29156643, 2017). "Moreover, DNMT3A, which also acts as a potential TGFB1 target, was found to be likely to mediate BRAFV600E epigenetic modifications in this study, thus facilitating melanoma development." (PMID 25890285, 2015).
prostate carcinoma (31 papers, 2009 to 2025). A carcinoma that arises from epithelial cells of the prostate gland. "Based on these results, we established a new feedback loop between DNMT3a and miR-340-5p/miR-143-3p/miR-145-5p underlying prostate cancer development." (PMID 33589600, 2021). "To explore the pathogenic functions of SChLAP/DNMT3a in prostate cancer, we further evaluated their influences on prostate cancer cell proliferation, migration, and in vivo tumorigenicity using both the cellular and animal models." (PMID 33589600, 2021). "A second individual, who had CM (at age 76 years), prostate cancer (at 86 years) and chronic myeloid leukaemia (at age 88 years), had a novel splice variant, 2bp into the intron after exon 18 of DNMT3A; this variant is of unknown functional consequence." (PMID 29641532, 2018). "In the NASA Twins Study, both career astronauts had increased mutational burden in epigenetic regulators such as DNMT3A and TET2 compared to prostate cancer patient controls." (PMID 38634106, 2024). "For example, lncRNA SChLAP1 was found to recruit EZH2 and DNMT3A to repress multiple miRNA expression in prostate cancer, including the miR-340-5p/miR-143-3p/miR-145-5p, these miRNAs in turn regulate DNMT3A expression." (PMID 36533073, 2022). "In this study, we demonstrated that the overexpression of DNMT3a effectively abrogated the SChLAP1 silencing-induced alterations of prostate cancer cell proliferation, migration, and tumor formation in nude mice, as well as miRNA expressional changes." (PMID 33589600, 2021). "Then, we constructed recombinant plasmids consisting of the C‐terminal domains of both Dnmt1 and Dnmt3a methyltransferases fused to a zinc finger domain that specifically bind to PD‐L1 promoter of prostate cancer cell line DU145." (PMID 31090214, 2019). "Meanwhile, DNMT3A has been highlighted as a key repressor of epithelial genes, including CDH1 and GRHL2, in a prostate cancer-associated fibroblast-induced EMT model." (PMID 31372511, 2019). "The biological significance of miR‐200c and miR‐141 expression in prostate cancer cells was assessed by a series of in vitro bioassays and the effect on proposed targets DNMT3A and TET1/TET3 was investigated." (PMID 27198154, 2016). "To explore the mechanism of negative regulation of miR‐146a by PVT1, we analyzed the level of three active DNA methyltransferases (DNMT1, DNMT3a, and DNMT3b) in prostate cancer cell lines using qRT‐PCR when PVT1 was aberrantly expressed." (PMID 27794184, 2016). "DNA chromatin remodeling proteins, such as EZH2, SUZ12, and DNMT3a, were also under-expressed, as observed in prostate cancer studies." (PMID 24504051, 2014). "Moreover, it has been confirmed that SChLAP1 facilitates prostate cancer progression by interacting with EZH2 to mediate DNA methylation of various miRNAs on chromosome 5 with a DNMT3A-feedback loop." (PMID 38890707, 2024). "Indeed, antiandrogen medication given to patient with prostate cancer increased DNMT3A and DNMT3B expression." (PMID 35360841, 2022). "Also, we proved here that the feedback loop between miR-340-5p/miR-143-3p/miR-145-5p and DNMT3a expression mediated the oncogenic roles of SChLAP1 in prostate cancer development." (PMID 33589600, 2021). "Importantly, we proved that miR-340-5p, miR-143-3p, and miR-145-5p commonly target the expression of DNMT3a in prostate cancer cells, which also repressed the expression of these miRNAs as a feedback loop in prostate cancer cells." (PMID 33589600, 2021). "Moreover, DNMT3a was one of the common target genes of miR-340-5p/miR-143-3p/miR-145-5p in prostate cancer cells." (PMID 33589600, 2021). "In this study, we also proved that DNMT3a could effectively repress the expression of miR-340-5p, miR-143-3p, and miR-145-5p in prostate cancer cells." (PMID 33589600, 2021). "In addition, PVT1 overexpression obviously increased the activity of DNA methyltransferases (DNMT1, DNMT3a, and DNMT3b) in prostate cancer cells." (PMID 27794184, 2016).
prostate carcinoma (continued). "Through bioinformatics, we predicted DNMT3a as a common target gene of miR-340-5p, miR-143-3p, and miR-145-5p, which was further validated by our following dual-luciferase reporter assay combined with transfecting prostate cancer cell with miRNA mimics and inhibitors." (PMID 33589600, 2021). "The variant in DNMT3A observed in haematological malignancies (p.R693H, as reported in COSMIC), was detected in an individual who had not developed such a tumour type prior to their death aged 89 years (previous cancers are: CM, prostate cancer and mesothelioma)." (PMID 29641532, 2018). "Our investigation into the impact of siRNA-mediated targeting of DNMTs (NDMT1, DNMT3A, and DNMT3B) on SPDEF expression in prostate cancer cells has yielded valuable insights." (PMID 37900138, 2023). "We analyzed the expression of DNMT1, DNMT3A, DNMT3B, and the class I HDACs HDAC1, HDAC2, HDAC3, and HDAC8 in the PRAD and Taylor data sets and their correlation to HLA-I expression in prostate cancer." (PMID 36050516, 2022). "We observed that both GSK343 and γ-Oryzanol promoted miR-340-5p, miR-145-5p, and miR-143-3p expression in prostate cancer cells, showing the regulation of miR-340-5p, miR-145-5p and miR-143-3p expression by EZH2 and DNMT3a." (PMID 33589600, 2021). "We assessed the effects of SFN and DIM on the expression of DNMT1, DNMT3A, and DNMT3B in normal prostate epithelial cells (PrEC), androgen-dependent (LnCAP) and androgen-independent (PC3) prostate cancer cells." (PMID 24466240, 2014). "We assessed the effects of SFN on the expressions of DNMTs (DNMT1, DNMT3a, and DNMT3b) in benign hyperplasia (BPH-1), LnCap and PC3 prostate cancer cells." (PMID 22303414, 2011). "We found that the most significantly changed epigenetic regulators in both prostate cancer tissues and cell lines were EZH2, SMYD3 and DNMT3A, which function as H3K27 trimethyltransferase, H3K4 di/tri-methyltransferase and DNA methyltransferase, respectively." (PMID 19262738, 2009). "In the complementary studies, we utilized small interfering RNA (siRNA) to selectively target pivotal DNA methyltransferases (DNMTs), including NDMT1, DNMT3A, and DNMT3B, with the primary objective of elucidating their roles in the modulation of SPDEF protein expression within prostate cancer cells." (PMID 37900138, 2023). "For further exploration of the possible involvements of EZH2 and DNMT3a in regulating miR-340-5p, miR-145-5p, and miR-143-3p expression, we next inhibited EZH2 and DNMT3a activity in prostate cancer cells using specific inhibitors and gene knockdown technology." (PMID 33589600, 2021). "Altogether, our results suggest that SChLAP1 enhanced the proliferation, migration, and tumorigenicity of prostate cancer cells through interacting with EZH2 to recruit H2K27me3 and mediate promoter methylation modification of miR-340-5p/miR-143-3p/miR-145-5p with a DNMT3a-feedback loop." (PMID 33589600, 2021). "Furthermore, SChLAP1 overexpression inhibited miR-340-5p/miR-143-3p/miR-145-5p expression in prostate cancer cells, which were abrogated by treatments with EZH2, H3K27me3, and DNMT3a inhibitors." (PMID 33589600, 2021). "Given that ERG is able to antagonize AR function in prostate cancer cells, it will be interesting to explore whether ERG regulation of YAP1 also relies on antagonizing the repressing actions of the AR/DNMT3a complex." (PMID 29383141, 2017). "Several studies have shown that the Polycomb repressive complex 2 (PRC2) subunit EZH2 and DNMT3a can cooperate for transcriptional repression; while the interaction between AR and EZH2 has recently been shown to be important for regulating genes in prostate cancer development." (PMID 29383141, 2017). "Our data clearly indicates that mahanine treatment causes a decline in the levels of DNMT1 and DNMT3B, without affecting the levels of DNMT3A, in both LNCaP and PC3 prostate cancer cells." (PMID 24001151, 2013).
prostate carcinoma (continued). "Interestingly, 3 out of 12 novel non-DDR genes (DNMT3A, HMBS and MYH7) were related to DNA methylation that contributes significantly to the development and progression of prostate cancer." (PMID 36095024, 2022).
glioma (28 papers, 2011 to 2026). A benign or malignant brain and spinal cord tumor that arises from glial cells (astrocytes, oligodendrocytes, ependymal cells). "For instance, SETD2 mutations are found in 10% of KIRC, 9% of non-small cell lung carcinomas, 15% of pediatric high-grade gliomas and 8% of adult high-grade gliomas, whereas mutations in DNMT3A are observed in over 20% acute monocytic leukemias." (PMID 30897760, 2019). "DNMT3A mutation was the most frequent among the m5C regulators in low‐grade glioma." (PMID 33400376, 2021). "Alteration of the key DNA methylation protein, DNMT3A, leads to increased proliferation and malignancy of human glioma through the TNF-α-NF-kB signaling pathway." (PMID 42135822, 2025). "Of interest, human GBM and IDH (isocitrate dehydrogenase)-wildtype glioma samples, which are known to have a higher activity of mTOR (TCGA), tended to display (p = 0.059) reduced expression of DNMT3A in comparison with “lower-grade gliomas”." (PMID 38481314, 2024). "It has been proved that DNMT3A inhibits the proliferation of human glioma cells and induces cell cycle arrest." (PMID 37934565, 2023). "For example, we reported that DNMT1 and DNMT3A were necessary for the methylation of the CASP8 promoter in glioma cells." (PMID 29449903, 2018). "For example, inhibition of the DNMT3A/ISGF3Υ interaction increased the response to temozolomide in glioma models." (PMID 29449903, 2018). "In particular, the increase of CYP17A1 was caused by Sp1-mediated DNA demethylation, whereby Sp1 competed with DNMT3a for binding to the CYP17A1 promoter in TMZ-resistant glioma cells." (PMID 28530704, 2017). "The occupancy of the methylation-related histones (H3K4me2, H3K27me3, H3K9me3 and H4K20me3) on the LMO3 promoter was detected after the inhibition of EZH2, EED and DNMT3A in glioma cells." (PMID 25829251, 2015). "Increasing dnMase activity is also supported by an increase in both Dnmt3a and 3b genes expression in glioma cells treated with folate in response to detachment of SP1 in favor of SP3 in these promoters." (PMID 24709797, 2013). "MiR-129-5p was found to target DNMT3A, and overexpression of this miR could inhibit human glioma cell proliferation and induce cell cycle arrest." (PMID 38003512, 2023). "MiR-129-5p by directly targeting DNMT3A could inhibit cell proliferation and induce G1 phase arrest in glioma." (PMID 33330110, 2020). "Hsa-miR-129-5p, a tumor suppressor, is down-regulated in gliomas and inhibits glioma proliferation, migration and development by targeting TGIF2, WNT5A, DNMT3A, HOXC10, FNDC3B." (PMID 35601497, 2022). "The results showed that NSUN4, NSUN7, DNMT1, DNMT3B, DNMT3A, NOP2 and NSUN5 were negatively correlated with the overall survival of low‐grade glioma, while NSUN6 was positively correlated with the overall survival." (PMID 33400376, 2021). "To study the role of DNMTs in gliomas, we used q-RT PCR to analyze the expression of the three DNA methyltransferase enzymes (DNMT1, DNMT3A and DNMT3B) in a panel of low and high-grade gliomas (n=32) collected at the University Medical Center Freiburg." (PMID 28036297, 2017). "Via lentiviral-mediated delivery into LN18 glioma cells, we employed deactivated Cas9-CRISPR technology to target the MGMT promoter and enhancer regions for methylation, as mediated by the catalytic domain of the methylation enzyme DNMT3A." (PMID 38224404, 2024). "ZDHHC5-mediated palmitoylation of EZH2 activates histone H3 Lysine 27 trimethylation (H3K27me3), suppresses miR-1275, elevates Glial Fibrillary Acidic Protein (GFAP) expression, and decreases DNA methyltransferase 3 alpha (DNMT3A) binding to the OCT4 promoter, contributing to glioma malignancy." (PMID 38067206, 2023).
glioma (continued). "CD133 knockdown increased the nuclear translocation of DNMT1 in CD133+ glioma cells without obviously changing the nuclear translocation of DNMT3a or DNMT3b." (PMID 35798319, 2022). "DNA methyltransferases DNMT3B, DNMT3A, and DNMT1 were comparatively overexpressed in the MS4A6A high expression subgroup, which might be the reason for MS4A6A hypomethylation in glioma tissues, leading to insight into upregulated mechanisms of MS4A6A in glioma." (PMID 36119086, 2022). "Yang et al51 reported that complex SUV39H1/CRL4B/HP1/DNMT3A promoted DNA methylation‐based epigenetic silencing, while Spyropoulou et al52 also showed that histone lysine N‐methyltransferases, especially SUV39H1, led to malignancy in gliomas and is a potential biomarker." (PMID 32281273, 2020). "Furthermore, transfection with miR-185 significantly reduced the levels of DNMT1 mRNA transcripts and protein expression in glioma cells, but did not affect the expression of DNMT3A and DNMT3B (data not shown)." (PMID 21962230, 2011). "Transfection of glioma cells with miR-185 significantly reduced the levels of DNMT1 mRNA transcripts and did not affect the expression of DNMT3A and DNMT3B." (PMID 38003512, 2023). "In glioma cells, DNA demethylation of promoters, following specific inhibition of DNMT1, DNMT3A, or DNMT3B, was not fully redundant suggesting the existence of different target patterns for these enzymes." (PMID 29449903, 2018).